INS (insulin)
Diseases named in the same sentence as INS in open-access papers (continued):
Sharing a sentence is not in itself a finding about the gene and the disease.
prediabetes (continued). "Impaired insulin secretion and action occur both in prediabetes and T2D patients." (PMID 29373500, 2018). "While the mechanisms underlying the second meal phenomenon are unclear, for individuals with T2D the second meal is potentiated by the insulin secretion in response to the first meal, as presently observed for responses to both large and small first-meals in individuals with prediabetes." (PMID 29882811, 2018). "In the current cross-sectional population-based cohort study, high glucose intake was associated with higher insulin sensitivity and a decreased odds of prediabetes, independent of dietary fibre." (PMID 28406435, 2017). "Future studies that focus on estimates of insulin secretory function in prediabetes subtypes may provide novel insights into the aspects of BCF covered by the several BCF indices." (PMID 27933333, 2017). "The oral glucose tolerance test revealed borderline diabetes with impaired insulin secretion." (PMID 29321794, 2017). "Therefore, the aim of the current study was to investigate the individual associations of glucose, fructose, and sucrose intakes with BCF and insulin sensitivity as primary outcomes, and with prediabetes and newly diagnosed T2DM as secondary outcomes." (PMID 28406435, 2017). "We have reservations to generalize our findings; however, appropriate early intervention in glycemic control and improvement in insulin sensitivity in the CM individuals may reduce the rate of prediabetes and T2D." (PMID 28713332, 2017). "On this basis, we would rather define it as “depression comorbid with prediabetes” in our present research, because decreases in islet insulin area, increased infiltrations of F4/80 positive inflammatory cell and disturbances of insulin secretion were observed simultaneously." (PMID 29084550, 2017). "The pancreatic insulin secretory capacity changes during the long period of prediabetes." (PMID 29046729, 2017). "Whether feeding immediately post-exercise has differential effects on insulin metabolism in an exercise intensity based manner though is unclear, particularly in a clinical population of adults with prediabetes." (PMID 27111219, 2016). "Given that impaired insulin sensitivity is observed prior to impaired FG and A1c in prediabetes, use of insulin resistance index may be superior to A1c or FG for early detection of prediabetes." (PMID 27298712, 2016). "All these functions are altered in the insulin sensitive tissues of prediabetes and T2DM." (PMID 26020947, 2015). "Initially, the changes can occur in a single signaling cascade in specific brain area and then extend to the other central signaling systems, which leads to deregulation of energy homeostasis and to decrease of insulin sensitivity, and finally to prediabetes state." (PMID 28031898, 2015). "Our study suggests that those with prediabetes may improve insulin sensitivity with calcium and vitamin D supplementation." (PMID 25299668, 2014). "Our investigation of Sox17 regulated transcripts clearly indicates a central role for this factor in regulating insulin secretory pathways, and it is possible that some of these might be deranged in prediabetes in humans." (PMID 25144761, 2014). "When stratifying our population in obese and non-obese participants as well as in insulin resistant and insulin sensitive participants, we found that the risk alleles associate with prediabetes only in the obese and insulin resistant groups." (PMID 22768041, 2012). "Restricting the investigated risk load on the genetic variants related mainly to insulin secretion (7 out of 9 SNPs) did not abolish, but rather strengthen the association with prediabetes." (PMID 22768041, 2012). "We furthermore tested associations of the T2D-related genetic risk with the presence of prediabetes in female/male, obese/non-obese and insulin resistant/sensitive strata of the cohort." (PMID 22768041, 2012).
prediabetes (continued). "In our earlier work with CPF, we established the presence of hyperlipidemia, but serum glucose levels were maintained within normal limits; however, glucose homeostasis was maintained only by compensatory hypersecretion of insulin, thus producing a metabolic profile akin to prediabetes." (PMID 20123610, 2010). "Thus, targeting insulin for brain health may have clinical implications since nearly 5 million Americans are living with Alzheimer's disease and almost 90 million have prediabetes." (PMID 39421964, 2025). "Thus, robust insulin secretion could be 1 of the mechanisms that explain the protection against incident prediabetes that was observed among participants with higher baseline eGFR in the present study." (PMID 41163811, 2025). "These combined actions address multiple aspects of glucose metabolism, including insulin secretion, glucose absorption, hepatic glucose production, and oxidative stress, highlighting the polyherbal formulation's multifaceted approach in managing T2D and prediabetes effectively." (PMID 40083990, 2025). "In this context, this study aimed to analyze the following: (a) insulin secretion, (b) insulin sensitivity levels, and (c) the level of IL-17 in peripheral blood in nondiabetic FDRs, divided into subgroups based on the stage of prediabetes, and in patients with R-T1D." (PMID 40004639, 2025). "Therefore, we analyzed whether IGF-1 had mediating roles in the relationship between insulin and androgen levels in women with prediabetes." (PMID 41384021, 2025). "Moreover, this exercise regimen appears to facilitate the unidentified novel Piezo2-mediated ultrafast proton-based synchronization pathways, thereby promoting more optimal insulin regulation in response to mechanotransduction, even in individuals with prediabetes." (PMID 40137805, 2025). "A 12-week intervention study found that although both exercise training and metformin significantly improved insulin sensitivity in individuals with prediabetes, data from the combined group suggested that metformin may attenuate the full beneficial effects of exercise training alone." (PMID 41357171, 2025). "In summary, GDM patients treated with insulin during pregnancy presented with a worse metabolic profile and elevate inflammation, including significantly higher BMI compared to GDM women without insulin treatment and Ctrl participants, and were at higher risk to develop prediabetes." (PMID 40129978, 2025). "From the results of our pilot study, it was observed that functional nutrition and lifestyle strategies reduce systemic inflammation and increase cell sensitivity to insulin, which could ultimately lead to improved blood sugar and inflammatory markers in prediabetes and T2DM." (PMID 39100011, 2024). "However, this inverse association was only significant in those with T2D (unless treated with insulin), in whom each serving of avocado was associated with HbA1c values that were ~7 mmol/mol lower, and not in those with normoglycemia or prediabetes." (PMID 37798236, 2023). "Therefore, enhancing skeletal muscle-specific PAK1 signaling could ameliorate muscle metabolic dysfunction, improve insulin sensitivity, reverse prediabetes and prevent progression to T2D." (PMID 37759961, 2023). "Indeed, high insulin levels in the brain, induced by prediabetes or T2D, may increase the hyperphosphorylation of tau protein." (PMID 37873836, 2023). "Furthermore, a recent study on the role of A2A AR in the whole-body insulin sensitivity in a prediabetes animal model, concluded that A2A adenosine antagonists restored impaired insulin signaling in the skeletal muscle of HSu rats, but did not affect the liver or adipose insulin signaling." (PMID 37143025, 2023).
prediabetes (continued). "There is also a need to elucidate whether initially high levels of systemic inflammation in obese individuals with T2DM and prediabetes can be lessened by alterations to diet and physical activity, and if this corresponds to improvements in glycemic control and insulin sensitivity." (PMID 37893600, 2023). "Vitamin D and omega-3 co-supplementation improved fasting serum glucose, insulin, high-density lipoprotein-cholesterol level, homeostasis model assessment beta cell function, weight, and waist circumference in women of reproductive age with prediabetes and hypovitaminosis D." (PMID 38068801, 2023). "Furthermore, a multiple linear regression analysis with 25(OH)D, insulin, and HOMA-IR as variables revealed that serum adiponectin levels could be an independent risk factor for the progression of prediabetes and T2DM." (PMID 38068801, 2023). "Prediabetes was less prevalent among survivors, while cohort members who died from cancer were of male predominance, with higher rates of smoking, with increased blood pressure and BMI, and with higher fasting glucose, insulin and total triglycerides plasma levels." (PMID 35921366, 2022). "Therefore, the promotion of anti-inflammatory diet might maintain glucose–insulin homeostasis, and subsequently lower the odds of insulin resistant and prediabetes." (PMID 35250879, 2022). "These eating behaviors may contribute to rapid glucose concentration and, subsequently, to a decrease in insulin secretion and β-cell dysfunction, which is a different contribution to the progression of prediabetes from insulin sensitivity related to BMI and its change." (PMID 36231160, 2022). "Indeed, early TRF improves insulin sensitivity, blood pressure, and oxidative stress in men with prediabetes, even without weight loss." (PMID 36451744, 2022). "Worsening of glucose tolerance from NGT to prediabetes to newly diagnosed T2DM in women was associated with a progressive increase in age-adjusted values of BMI, waist circumference, heart rate, triglycerides, fasting insulin, HOMA-IR, and a decrease in HDL cholesterol." (PMID 33676510, 2021). "Furthermore, improved insulin sensitivity may have enhanced carbohydrate loading in the exercising prediabetes animals thus shunting some glucose towards glycogen storage in the muscle and liver in preparation for the next exercise training." (PMID 33888141, 2021). "Therefore, we rejected the null hypothesis and confirmed intercorrelation between the immune system, EOS, and insulin in prediabetes." (PMID 34099024, 2021). "Hence, the mechanism remains unclear, and it is unexplored what the relation between glucose metabolism, insulin, and cardiac function is in prediabetes." (PMID 34827678, 2021). "An animal study showed that a HIF inhibitor may improve IR in high-fat diet mice, while in humans, a recent randomized controlled trial discovered that two weeks of eight hours nightly of continuous positive airway pressure increased insulin sensitivity in prediabetes." (PMID 34209501, 2021). "Therefore, to test whether HIIT could improve glucose control and insulin sensitivity in older adults with prediabetes we opted to utilize and modify our previous 10 week HIIT program." (PMID 32431698, 2020). "Notably, individuals with prediabetes may have a reduced response to diet-induced microbiota modulation with respect to host insulin sensitivity and metabolic health outcomes." (PMID 32122428, 2020). "However, when the insulin signaling pathway is impaired in prediabetes, de novo lipogenesis is still elevated due to the substrate push mechanism in which there is increased substrate delivery to the liver followed by increased esterification of fatty acids into triglycerides." (PMID 32149046, 2020).
prediabetes (continued). "In the present study, the higher insulin and HOMA-IR values observed in the subjects with TSAT<20% are in agreement with some results of the EPIC-InterAct prospective study, the KORA F4 study, and the US NHANES, all of them showing associations between low TSAT and prediabetes." (PMID 32821534, 2020). "Also, prediabetes with high insulin levels appears to increase TNF-α in patients." (PMID 31992349, 2020). "Indeed, we have shown that changes in circulating FFAs following moderate intensity training are directly related to improved peripheral insulin sensitivity and short-term interval or continuous exercise increases adipose insulin sensitivity in adults with prediabetes." (PMID 32849302, 2020). "Therefore, the finding of greater serum kisspeptin levels in pubertal patients with prediabetes HbA1c as compared with those with normal HbA1c might be related to the stimulatory effect of kisspeptin on insulin secretion to compensate for insulin resistance." (PMID 33224197, 2020). "Moreover, in the present conditions we did not observe any associations with insulin sensitivity, which have been reported before, although our participants still presented with the characteristics of prediabetes." (PMID 32333763, 2020). "Therefore, we speculate that the absent cold-induced changes in ANGPTL3 and ANGPTL8 in middle-aged men with overweight and prediabetes might reflect an attempt of the body to overcome impaired glucose uptake by insulin-resistant BAT." (PMID 31416197, 2019). "This possibility is of interest in patients with normal triglyceride levels but signs of prediabetes or resistance to insulin; we observed that GRP78/BiP was already high in these patients, suggesting that other metabolic alterations might play a role in GRP78/BiP secretion." (PMID 31717752, 2019). "Therefore, it may be possible that mothers with prediabetes had increased levels of insulin and sugars in breast milk." (PMID 28212335, 2017). "However, there may be a benefit of treatment on insulin sensitivity in participants with prediabetes." (PMID 25299668, 2014). "However, in those with prediabetes, there could be a beneficial treatment effect on insulin sensitivity, but these results need to be interpreted with caution given the post hoc nature of the analysis." (PMID 25299668, 2014). "However, in participants with prediabetes, supplementation with vitamin D and calcium may improve insulin sensitivity." (PMID 25299668, 2014). "The mediation model indicated that elevated insulin increases serum total testosterone directly, and indirectly through increasing IGF-1 in women with prediabetes." (PMID 41384021, 2025). "In the clinical treatment of prediabetes, combining MIAE and metformin often enhances glycemic control and insulin sensitivity." (PMID 41428169, 2025). "The potential mechanisms by which VAI and LAP influence the outcome of prediabetes may include: Visceral fat exhibits high lipolytic activity, leading to an increased free fatty acid load in the portal circulation, which promotes hepatic fat accumulation and insulin resistance." (PMID 39348367, 2024). "By improving insulin sensitivity, PPARG helps maintain glucose homeostasis, an important factor in preventing the progression from prediabetes to T2DM." (PMID 39767130, 2024). "Particularly, HAdV-36-positive females with prediabetes presented with decreased HOMA-IR and lower serum insulin levels relative to seronegative counterparts." (PMID 38932214, 2024). "Beta cells possess an inherent resilience in early and prediabetes, and, likely, until the beta cells completely ‘peter out’ late in the course of the disease.Beta cells may enlisted back into service by easing the nutrient overload or insulin resistance that is taxing beta cells, as example." (PMID 38933821, 2024). "In addition, in a prediabetes state, elevated plasma insulin levels may be found." (PMID 39201522, 2024).
prediabetes (continued). "The downregulation of caveolin-1 in the prediabetes group compared to normoglycemic individuals in our study could imply insufficient exercise among our patients and a possible transition from normoglycemia to a prediabetic state, which could impair caveolae function and insulin signaling." (PMID 39085321, 2024). "The study population consisted of two groups of women with prediabetes and mildly elevated TSH levels, matched by age, insulin sensitivity, TSH, and thyroid hormone levels." (PMID 38051473, 2024). "The mean levels of glucose (104.92±4.27), HbA1c (5.77±0.39), insulin (16.63±10.38), and HOMA-IR (4.30±2.26) were significantly higher in individuals with prediabetes compared to healthy individuals." (PMID 39081429, 2024). "Significant differences were observed in insulin concentrations at timepoint 0, 1h-PG, 1.5h-PG, and 2h-PG between the groups prediabetes and NGT, with higher insulin concentrations in the prediabetes group." (PMID 39125447, 2024). "Similar results were also seen in a crossover trial involving men with prediabetes, in which 5 weeks of TRE with a 6-h eating window early in the day reduced the concentrations of insulin both in the fasting state and during a 3-h OGTT18." (PMID 39341847, 2024). "Waist circumference and the majority of metabolic endpoints were significantly higher in the group with prediabetes, including FPG, insulin, HbA1c, HOMA-IR, total and LDL-C, and TG (all, p < 0.01)." (PMID 38999851, 2024). "The PDI group had reduced total cholesterol, HDL cholesterol, insulin concentrations, and HOMA-IR after 10 weeks of dietary intervention compared to the prediabetes control (PDC) group (p < 0.05)." (PMID 38732508, 2024). "A significant difference in fasting insulin concentration was observed between prediabetes-IDF and IH-1h (with the lowest fasting insulin concentrations among all groups in IH-1h)." (PMID 39125447, 2024). "Changes in serum adiponectin or serum 25(OH)D in people with prediabetes and T2DM were inversely related to serum insulin levels." (PMID 38068801, 2023). "For Matsuda insulin sensitivity index, only VAT volume (β = − 1.210, p = 0.004) was the only significant factor in individuals with prediabetes." (PMID 37864066, 2023). "Prediabetes and T2DM were diagnosed by fasting glucose, glycohemoglobin, and self-reported medication or insulin." (PMID 38075228, 2023). "Approximately one-third of GDM patients in the institution require insulin or OAD for glycemic control, which represents an important predictor of prediabetes postpartum." (PMID 37680834, 2023). "Several trials have studied the effect of exercise on insulin secretion in individuals with T2DM and prediabetes, as well as in sedentary overweight or obese subjects." (PMID 37836486, 2023). "The present model of prediabetes demonstrates impaired glucose homeostasis, as indicated by variations in glucose tolerance such as fasting blood glucose, OGTT, and insulin levels." (PMID 37324274, 2023). "The brown cluster contained some common measures of prediabetes, such as IFG, IGT, OGTT, insulin secretion, and insulin sensitivity." (PMID 36908460, 2023). "Notably, skeletal muscle insulin action may decline years before prediabetes manifests." (PMID 37048823, 2023). "In the pathogenesis of prediabetes and T2DM, inflammatory response, nutrition, intestinal permeability, glycolipid metabolism, insulin sensitivity, and energy homeostasis play an important role." (PMID 38068801, 2023). "In the sensitivity analysis among women with insulin data (NFG/NGT = 1705 and prediabetes = 422), similar results to the original population were observed when we included HOMA-IR in place of FPG in our data analysis." (PMID 36732786, 2023). "In humans, clinical trials aiming to boost endogenous NAD+ for treatment of metabolic diseases are increasing, showing promising results; for example, in postmenopausal women with prediabetes, a daily dose of NMN increases muscle insulin sensitivity." (PMID 36973248, 2023).